CTCF (CCCTC-binding factor)
Diseases named in the same sentence as CTCF in open-access papers (continued):
Sharing a sentence is not in itself a finding about the gene and the disease.
B-cell lymphoblastic leukemia (3 papers, 2019 to 2025). "For these studies, the B-cell lymphoblastic leukemia cell line SEM with constitutive expression of OsTIR1(F74G), endogenous CTCF-miniAID-mClover (CTCFAID2), and inducible exogenous HA-tagged wild-type CTCF (CTCFAID2/WT) or RBR deficient CTCF (CTCFAID2/dRBR) were used." (PMID 40355969, 2025).
Beckwith-Wiedemann syndrome (3 papers, 2020 to 2023). Beckwith-Wiedemann syndrome (BWS) is a genetic disorder characterized by overgrowth, tumor predisposition and congenital malformations. "CTCF site-specific deletions were shown to be associated with imprinting in the IGF2/H19 locus, causing Beckwith-Wiedemann syndrome (BWS; OMIM 130650)." (PMID 33863876, 2021). "TGF-β, together with the tumor suppressor CTCF, epigenetically and/or transcriptionally regulate tumor promoter genes, including IGF2, TERT, and Myc in TGF-β–defective mice and in patients with Beckwith-Wiedemann syndrome (BWS), a human stem cell disorder." (PMID 33457451, 2020).
bladder cancer (3 papers, 2018 to 2023). "To better assess the role of FOXA1 in the regulation of bladder cancer SEs, we mapped FOXA1, CTCF (Insulator/enhancers) and H3K4me3 (Promoter) binding by ChIP-seq in two bladder cancer cell lines: SD48 (LumP) and 5637 (Ba/Sq)." (PMID 36944729, 2023). "H19 promoter region can bind to CCCTC-binding factor (CTCF) and insulin like growth factor 2 (IGF2), and thereby regulating bladder cancer development in nucleus of BC cells." (PMID 34422802, 2021).
chronic myelogenous leukemia (3 papers, 2015 to 2024). "Finally, we investigated the cell-type specificity of the response to deletion of the regions encompassing the PCa risk-associated CTCF sites by also deleting these regions in HEK293T kidney cells and HAP1 chronic myelogenous leukemia cells." (PMID 30296942, 2018). "As a model, we used human chronic myelogenous leukemia (K562) cells, a cell line where BORIS is endogenously expressed and CTCF and BORIS binding sites have been previously mapped." (PMID 38297316, 2024).
COVID-19 (3 papers, 2021 to 2026). A disease caused by infection with severe acute respiratory syndrome coronavirus 2. "This in silico analysis indicated that CTCF might be involved in COVID-19 pathogenesis and require further experimental validation." (PMID 34940755, 2021).
Down syndrome (3 papers, 2018 to 2022). "In humans, Down syndrome–related acute megakaryoblastic leukemia carries CTCF deletions or mutations in 20% of all cases." (PMID 36037342, 2022). "However, Down syndrome–related megakaryoblastic leukemia appears to reveal a role for dysfunctional CTCF in tumor progression within the hematopoietic compartment." (PMID 36037342, 2022).
endometrial tumours (3 papers, 2017 to 2019). "Mutations in PTEN, ARID1A, PIK3CA, PIK3R1, beta-catenin, CTCF, and KRAS, are often found in endometrial tumors with endometrioid histology, with a mutation in at least one of these genes found in 94% of tumors." (PMID 30712080, 2019). "Collectively CTCF was more likely to be deleted in endometrial tumours that developed relapse or metastasis than primary malignancies (P=0.0268, Fisher’s exact test)." (PMID 28319062, 2017). "Therefore, in CTCF haploinsufficient endometrial tumours, FOXA1/ER interactions with chromatin may increase leading to upregulation of estrogen-responsive genes." (PMID 30513694, 2018). "Many of these genes appear to be specific to endometrioid endometrial tumors, as opposed to nonendometrioid endometrial tumors, including transcriptional regulators ARID1A, beta-catenin, and CTCF, indicating that there may be a connection between these mutations and estrogen signaling." (PMID 30712080, 2019).
gastrointestinal stromal tumor (3 papers, 2020 to 2024). "In several cancer types, including glioma and gastrointestinal stromal tumors, the integrity of chromatin loops fashioned by insulator CTCF–CTCF homodimerization is compromised, a consequence attributed to the methylated state of CTCF‐binding sites, which precludes CTCF binding." (PMID 38374872, 2024). "Many cases of CTCF disruption have been associated with changes in DNA methylation such as in isocitrate dehydrogenase (IDH) mutant gliomas, succinate dehydrogenase (SDH)-deficient gastrointestinal stromal tumors (GIST), and immunoglobulin or T cell receptors." (PMID 32933554, 2020).
Infertility (3 papers, 2022 to 2023). "Studies have discovered that the suppression of CTCF protein expression in spermatocytes can cause spermatogenesis disorders and infertility." (PMID 37235262, 2023). "There is evidence that CTCF plays a critical role during spermatogenesis as its depletion produces abnormal sperm and infertility." (PMID 37065848, 2023). "CTCF-null embryos could not implant and died by pre-implantation, and conditional CTCF KO mice were infertile with a 90% reduction in sperm count." (PMID 34731408, 2022).
Mental retardation, autosomal dominant 21 (3 papers, 2019 to 2025). "Pathogenic variants in the transcription factor CCCTC-binding factor (CTCF) are associated with mental retardation, autosomal dominant 21 (MRD21, MIM#615502)." (PMID 36847142, 2023). "In addition to the typical features of autosomal dominant mental retardation 21 (MRD21), CTCF mutations also manifest as a broader spectrum of organ developmental abnormalities, affecting the teeth, fingers, bones, heart, urinary, and reproductive systems." (PMID 39682078, 2025).
Parkinson disease (3 papers, 2020 to 2021). A progressive degenerative disorder of the central nervous system characterized by loss of dopamine producing neurons in the substantia nigra and the presence of Lewy bodies in the substantia nigra and locus coeruleus. "Among these factors, CTCF, MEF2A, and STAT3 have been associated with Alzheimer’s, Huntington’s, and Parkinson’s diseases." (PMID 34720873, 2021). "The lack of repressive signaling from CTCF could contribute to the observed increases in NEFM reported in Parkinson’s disease patients and the observed overexpression of NEFM associated with cytoplasmic inclusions in motor-impaired mice." (PMID 32178731, 2020).
rhabdoid tumor (3 papers, 2021 to 2023). An aggressive malignant embryonal neoplasm usually occurring during childhood. "This interaction of ncSWI/SNF with CTCF perhaps directs dysregulated promoter enhancer interactions that have previously been described in rhabdoid tumor." (PMID 33332735, 2021). "Interestingly, the most specifically enriched motif for the P81S11/2 HA peak set was CTCF/BORIS, which has been linked to the formation of SMARCB1 mutant rhabdoid tumors and the maintenance of a naive pluripotent stem cell state." (PMID 37554444, 2023). "Non-canonical complexes (ncBAF) localize to the transcriptional repressor CTCF (also known as 11-zinc finger protein or CCCTC-binding factor) and can act as synthetic lethal targets specific for synovial sarcoma (SS) and malignant rhabdoid tumor (MRT) or other cBAF-disrupted cancers." (PMID 36844227, 2023).
thyroid cancer (3 papers, 2020 to 2025). "Although this is beyond the scope of this paper, the role of genomic insulator CTCF, which likely determines long-distance interactions as well as the contribution of DNA methylation and allele-specific histone marks, which were recently characterized in thyroid cancer cell lines, are worth noting." (PMID 35053525, 2022). "Further investigation in an independent thyroid cancer cohort revealed a negative correlation between HN1 and CTCF, with HN1 inhibition enhancing CTCF expression in ATC cells." (PMID 40819127, 2025). "Interestingly, CTCF was observed not to bind to TERT in normal thyroid tissue despite the presence of methylation, while thyroid cancer cell lines exhibited both partial methylation and CTCF binding." (PMID 33329574, 2020).
Acheiropodia (2 papers, 2021 to 2023). "For example, the importance of CTCF for facilitating enhancer-promoter interactions is underlined by the discovery that patients with acheiropodia harbour mutations ablating a cluster of CTCF sites upstream of the Shh limb enhancer, ZRS, which facilitate interaction with the Shh gene." (PMID 37931379, 2023). "In the cells from the proband with acheiropodia, these sites are deleted and this interaction is substituted with another CTCF site (LSC1) centromeric to the ZRS." (PMID 33863876, 2021). "In summary, while we cannot conclusively rule out that alteration of the TAD boundary is responsible for this phenotype, our results strongly suggested that removal of these CTCF sites in humans alters the interaction between ZRS and the SHH promoter, likely leading to the acheiropodia phenotype." (PMID 33863876, 2021).
ADNP syndrome (2 papers, 2022). "We conclude that heterozygous ADNP mutations that cause ADNP syndrome result in both R-loop and CTCF alterations across the genome." (PMID 35013239, 2022). "Additionally, patient-derived human induced pluripotent stem cells that contain the prevalent ADNP syndrome-causing mutation p719* exhibit R-loop and CTCF accumulation at ADNP targets." (PMID 35399934, 2022). "Notably, patient-derived human induced pluripotent stem cells that contain an ADNP syndrome-causing mutation exhibit R-loop and CTCF accumulation at ADNP targets." (PMID 35013239, 2022). "We uncovered R-loop deregulation at specific sites in an ASD, ADNP syndrome, that correlate with CTCF alterations." (PMID 35013239, 2022).
Anxiety (2 papers, 2022). Intense feelings of nervousness, tension, or panic often arise in response to interpersonal stresses. "Mice with deletion of CTCF in parvalbumin-expressing neurons induced a decrease in anxiety-like behavior and a social impairment at early age, followed by gradual deficits in motor function." (PMID 35379308, 2022). "We have demonstrated that mice with CTCF cKO in PV-expressing inhibitory neurons exhibit reduction in anxiety-related behavior, less sociability and a decline in motor performance over time." (PMID 35379308, 2022). "Furthermore, changes in CTCF looping around genes such as Adcyap1 and Thbs2 are associated with sex- and oestrous cycle-dependent gene expression differences and further provide a possible link between 3D genome changes and anxiety-related behavioural phenotypes." (PMID 35705546, 2022). "Thus, three separate tests indicate that low expression of CTCF in PV inhibitory neurons leads to decline anxiety-related behavior at a developmental time point that is distinct from motor deficits." (PMID 35379308, 2022). "Anxiety-related tests were then performed on the CTCF cKO mice at the same time period." (PMID 35379308, 2022). "Therefore, at 2 months of age, the CTCF-cKO mice showed less anxiety-like behavior." (PMID 35379308, 2022).
atherosclerosis (2 papers, 2019 to 2021). A disease characterized by the build-up of fatty material and calcium deposition in the arterial wall resulting in partial or complete occlusion of the arterial lumen. "Moreover, opposite results were found in the aortic tissues of atherosclerosis mice treated with H19 or CTCF overexpression." (PMID 31757932, 2019). "H19 was capable of recruiting CTCF to suppress PKD1, thus promoting atherosclerotic vulnerable plaque formation and intraplaque angiogenesis in atherosclerosis mice." (PMID 31757932, 2019). "The present study provides evidence that H19 recruits CTCF to downregulate the expression of PKD1, thereby promoting vulnerable plaque formation and intraplaque angiogenesis in mice with atherosclerosis." (PMID 31757932, 2019). "This study aimed to explore the interactions among long non-coding RNA H19, transcriptional factor CCCTC-binding factor (CTCF) and polycystic kidney disease 1 (PKD1), and to investigate its potentially regulatory effect on vulnerable plaque formation and angiogenesis of atherosclerosis." (PMID 31757932, 2019).
colon adenocarcinoma (2 papers, 2020 to 2021). "For instance, a CTCF site near FOXC1 overlaps with recurrent deletions in esophageal, gastric and colon adenocarcinomas." (PMID 32024999, 2020).
Cornelia de Lange syndrome (2 papers, 2013 to 2017). A rare syndrome characterized by low birth weight, delayed growth, intellectual disabillity, behavioral problems, and a distinctive facial appearance (thin, arched eyebrows, low set ears, small teeth, and small nose). "In addition, cohesin proteins play a role in the regulation of chromosome organization and gene expression by binding to unmethylated CTCF-associated regions and mutations at cohesin genes are associated with the developmental defects seen in patients with Cornelia de Lange syndrome." (PMID 28293299, 2017).
depression (2 papers, 2022 to 2024). "Five of these TFs, namely ETS1, TFAP2A, NFKB2, CTCF, and RELA, are significantly deregulated in the blood samples of depression patients compared to controls (GSE217811 and GSE23848)." (PMID 38256187, 2024).
endometrioid carcinoma (2 papers, 2017 to 2022). "Enrichment analyses of COSMIC mutations of the CTCF ORF across 24 different tissue types revealed that approximately 20% of CTCF mutations were associated with endometrioid carcinoma." (PMID 36117989, 2022). "Within the 23 primary samples only a single grade 2 endometrioid carcinoma showed CTCF deletion." (PMID 28319062, 2017).
esophageal squamous cell carcinoma (2 papers, 2021 to 2023). Esophageal squamous cell carcinoma (ESCC) is a type of esophageal carcinoma (EC) that can affect any part of the esophagus, but is usually located in the upper or middle third. "As a transcriptional repressor, the CCCTC-binding factor (CTCF) can regulate the transcriptional inactivation of miR-137 to promote the expression of paxillin to promote EMT and radioresistance in esophageal squamous cell carcinoma." (PMID 37175948, 2023).
Ewing sarcoma (2 papers, 2022 to 2024). A small round cell tumor that lacks morphologic, immunohistochemical, and electron microscopic evidence of neuroectodermal differentiation. "A previous study showed reduced CTCF-anchored loop extrusion in STAG2 deficient Ewing sarcoma cells based on CTCF HiChIP data." (PMID 39487368, 2024). "To test this possibility, we analyzed the genomic distribution of EWS::FLI1, cohesin, H3K27ac, p300, and CTCF using available ChIP-seq data from different Ewing sarcoma cell lines (Table EV1)." (PMID 39487368, 2024). "In Ewing sarcoma A673 cells, non-CTCF cohesin sites were detected with an antibody against SMC1, but they showed little enrichment for RAD21, STAG1 or STAG2." (PMID 36424654, 2022).
HCMV infection (2 papers, 2021 to 2025). "Accessible chromatin regions that closed upon HCMV infection were highly enriched for predicted TEAD sites and depleted of CTCF (CCCTC-binding factor) sites in both human fibroblasts and retinal epithelial cell lines." (PMID 40928347, 2025).
head and neck cancer (2 papers, 2016). A primary or metastatic malignant neoplasm affecting the head and neck. "Mutational analysis highlighted a potential role for CTCF, a crucial regulator of long-range chromatin interactions, in head and neck cancer progression." (PMID 26747525, 2016).
ischemia (2 papers, 2021 to 2022). A hypoperfusion of the BLOOD through an organ or tissue caused by a PATHOLOGIC CONSTRICTION or obstruction of its BLOOD VESSELS, or an absence of BLOOD CIRCULATION. "From them all, the CCCTC-binding factor (CTCF), the glucocorticoid receptor (NR3C1), and the nuclear respiratory factor 1 (NRF1) were connected to nodes exhibiting opposite regulation at revascularization and post-conditioning versus ischemia." (PMID 35216205, 2022).
liver fibrosis (2 papers, 2022 to 2023). "However, whether and how CTCF plays a role in liver fibrosis and the relationship between PDLIM1 and CTCF during HSCs activation remains unclear." (PMID 37414929, 2023). "Gardenoside can ameliorate lipid deposition and liver fibrosis, and has been shown to decrease the expression levels of dipeptidyl peptidase-4 (DPP4), CCCTC-binding factor (CTCF), NLRP3, ASC, caspase-1 p20, GSDMD-N, and IL-1β in vitro and in vivo NAFLD models." (PMID 36016562, 2022). "Therefore, the role of CTCF in the process of liver fibrosis and how CTCF helps PDLIM1 promote liver fibrosis is worth exploring." (PMID 37414929, 2023).
malaria (2 papers, 2021 to 2023). Malaria is a serious and sometimes fatal disease caused by a parasite that commonly infects a certain type of mosquito which feeds on humans. "The human malaria parasite P. falciparum executes complex transcriptional programs and has a sophisticated genome organization considering that it encodes relatively few specific transcription factors and lacks key canonical genome organizing factors such as CTCF and lamins." (PMID 37592911, 2023). "In malaria parasites, those architectural proteins such as CCCTC binding factor (CTCF) or lamins, which are known to be involved in chromosome organization in metazoans, have not yet been identified." (PMID 33906919, 2021).
multiple myeloma (2 papers, 2015 to 2020). "In plasmablasts, IRF4 acquires an association with CTCF, a feature maintained in plasma cell myeloma lines." (PMID 32843533, 2020). "At the same time in plasmablasts, and in myeloma cell lines, IRF4 acquires a new association with the occupancy pattern of CTCF, suggesting a potential role in chromatin looping." (PMID 32843533, 2020).
pancreatic ductal adenocarcinoma (2 papers, 2022 to 2024). An infiltrating adenocarcinoma that arises from the epithelial cells of the pancreas. "For example, in pancreatic ductal adenocarcinoma, the knockdown of CCCTC-binding factor (CTCF) resulted in the downregulation of specific biomarkers of M2-like tumor-associated macrophages (TAMs), such as Mrc1 and CD163, reducing invasion and metastasis capabilities." (PMID 39033109, 2024).
prostate tumors (2 papers, 2020 to 2024). "CTCF deletion is specifically associated with increased methylation at CTCF binding sites in breast and prostate tumors." (PMID 32503656, 2020). "In prostate tumors, a comparison of absolute mean methylation (β-values) in CTCF CN loss versus CTCF diploid tumors demonstrated 1786 differentially methylated probe sets using a restrictive FDR cut-point (absolute value log2-β-values > 0.5; FDR q < 0.01)." (PMID 32503656, 2020). "These included EZH2 in DNA hypermethylated regions of prostate tumors in AA and EA men and CTCF in hypomethylated regions of only prostate tumors in AA men." (PMID 38566104, 2024). "This, along with our findings, suggests the enrichment of CTCF in DNA hypomethylated regions can potentially regulate gene expression specifically in prostate tumors of AA men and will be investigated in the future." (PMID 38566104, 2024). "We show that hypomethylated regions are enriched in transcriptional regulators, including CTCF, only in prostate tumors of AA men." (PMID 38566104, 2024). "Olfactory/ribosomal pathways and distinct cofactors, including CTCF and KMT2A, were enriched in DNA hypomethylated regions in prostate tumors from AA men." (PMID 38566104, 2024). "LISA-derived prediction showed enrichment of chromatin-remodeling enzymes, including CTCF and KMT2A, at hypoDMRs of prostate tumors from AA men but not EA men." (PMID 38566104, 2024).
Rett syndrome (2 papers, 2024 to 2026). A severe neurodevelopmental disorder affecting the central nervous system.